EGFR (epidermal growth factor receptor)
Diseases named in the same sentence as EGFR in open-access papers (continued):
Sharing a sentence is not in itself a finding about the gene and the disease.
cancer (continued). "Thus, this study demonstrated for the first time the direct association of EGFR and EREG with chronic pain in a clinical cohort of patients and further advocates the use of EREG/EGFR inhibitors as potential analgesics in the management of non-cancer pain in humans." (PMID 32547536, 2020). "However, whether IRX4 regulate the cancer stem-like properties of EGFR-TKI resistant cells needs further study." (PMID 32820157, 2020). "Therefore, EGFR was selected as a potential target for anti-cancer antibodies." (PMID 33324546, 2020). "For example, prospective studies on the expression of EGFR and EpCAM might shed light on the power of EpCAM expression to predict treatment response in carcinoma entities that implement a therapy with the anti-EGFR monoclonal antibody cetuximab or small molecule inhibitors of EGFR." (PMID 32507912, 2020). "Thus, EGFR activation and autophosphorylation is suppressed in 4.1B-sufficient cancer cells." (PMID 31492173, 2019). "Moreover, SERS could be a quite powerful tool for early diagnosis of overexpression of cancer-related proteins, such as CA IX and EGFR, exposed on the cell membrane." (PMID 30755643, 2019). "Intrinsically, our studies indicated that EGF-induced de novo Grb7 tyrosine phosphorylation/activation is essential for the tumorigenicity, suggesting that expression and activation of both Grb7 and EGFR might collaboratively function as a critical point in cancer developmental processes." (PMID 31083325, 2019). "Furthermore, TKIs or mAbs do not cause DNA fragmentation in many types of EGFR-positive cancer cells while their growth inhibition effects are obvious." (PMID 31508364, 2019). "While this suggests that the cancer cells have a potential path to immune escape, the EGFRvIII+ cancer cells are more resistant to chemotherapeutic agents such as paclitaxel and cisplatin and a subclonal population of EGFRvIII+ cells can promote survival of EGFR wt neighbors." (PMID 30601871, 2019). "Consequently, the EGFR has emerged as the target of effective cancer therapies." (PMID 31759360, 2019). "However, the more subtly activating substitutions may nonetheless contribute to cancer in cells with high levels of active kinases such as upon the overexpression of EGFR or other growth factor receptors—situations with widespread clinical relevance." (PMID 31889510, 2019). "This may explain the variable response to anti-EGFR treatment in these cancer patients." (PMID 31635038, 2019). "Interestingly, STAT3 activation seems to be a general mechanism of acquired resistance since it was also observed in cancer cells driven by diverse kinases, including EGFR, HER2, ALK, and MET, as well as mutant KRAS following treatment with specific inhibitors." (PMID 30622697, 2019). "Thus, we sought to determine whether EGFR pathway was involved in the regulation of the expression of P-gp and the sensitivity of cancer cells to VCR by IVM." (PMID 31215501, 2019). "Therefore, EGFR-targeted inhibitors, including tyrosine kinase inhibitors (TKIs) and monoclonal antibodies (mAbs) have been developed for its use in the treatment of several cancers." (PMID 31370270, 2019). "EGFR and HER2 can form homodimers or heterodimers after activation to activate intracellular signaling pathways, such as RAS/RAF/MEK/ERK, PI3K/AKT/mTOR, Src kinase, and STAT transcription factors associated with tumorigenesis, cancer progression, and drug resistance." (PMID 30952931, 2019). "Furthermore, the conjugation of the aptamer specific for EGFR with the immunomodulatory 10_12 mAb allowed also for the efficient redirection and activation of T cells against cancer cells, thus dramatically enhancing the cytotoxicity of the two conjugated partners." (PMID 31470510, 2019). "In addition, DYRK1A suppression by siRNA or an inhibitor could increase the anti‐cancer activity of AZD9291 in EGFR wild‐type NSCLC cells." (PMID 31454149, 2019).
cancer (continued). "Once activated, M3R transactivates EGFR and both receptors initiate cascades of protein kinase activation leading to changes in gene transcription and protein expression that increase cell proliferation, stimulate tissue invasion and promote cancer cell dissemination." (PMID 30841571, 2019). "Based on these considerations, we propose that DUOX1 activation during ligand-dependent EGFR activation may play an important role in regulating EGFR internalization and recycling, which may therefore be disturbed in cancer cells that lack DUOX1, in favor of nuclear EGFR localization." (PMID 30890751, 2019). "Consequently, inactivation of EGFR signaling pathway is a target for cancer treatment." (PMID 31681765, 2019). "In addition, the results of our study may also help to explain the molecular mechanism of the more frequent S. aureus infections in cancer patients treated with EGFR (epidermal growth factor receptor) inhibitors." (PMID 31744223, 2019). "Thus, several anti-EGFR drugs have been developed for clinical use in cancer therapy, including the small-molecule tyrosine kinase inhibitors (TKIs) gefitinib, erlotinib, afatinib, neratinib, dacomitinib, and osimertinib, as well as the monoclonal antibodies cetuximab and necitumumab." (PMID 31137590, 2019). "Specifically, miRNA-7 was found to inhibit epidermal growth factor receptor (EGFR) expression in human cancer cells and EGFR signaling is required for cumulus cell expansion and oocyte maturation, suggesting that miRNA-7 may negatively regulate oocyte maturation." (PMID 31562810, 2019). "Whether EGFR inhibitors also influence TRPM7 in cancer patients is unclear." (PMID 30995736, 2019). "The main aim of this study was to find a second target involved in the EGFR pathway to be targeted alone or in combination with current therapies (TKIs) in order to reduce TKIs dosage and hence their side effects, as well as the multi-drug resistance often acquired by cancer cells." (PMID 31635301, 2019). "EGFR and platium have been reported to be involved in the treatment of cancer, and through these enriched genes we may be able to discover specific mechanisms of drug resistance." (PMID 32063918, 2019). "Considering these observations, sHRG expression may potentially be associated with resistance to EGFR-TKIs, regardless of cancer type, and confirmation of this relationship in an unbiased study is warranted." (PMID 31862929, 2019). "Indeed, activation of mutated KRAS cancer cells is highly dependent on RAD51 for survival, KRAS mutation-dependent AKT1 stimulates HR and NHEJ activities for DNA DSB repair, and nuclear translocation of EGFR is associated with DNA-PKs for DSB repair." (PMID 31554189, 2019). "Therefore, modulation of EGFR represents a good strategy for cancer therapy." (PMID 31590362, 2019). "Therefore, EGFR can be a target for the development of anti-cancer therapy." (PMID 31527477, 2019). "In addition, the crosstalk between leptin and epidermal growth factor receptor (EGFR) signaling pathways could alter significantly the behavior of different cell types in cancer." (PMID 31380268, 2019). "Therefore, in addition to helping understand the regulation of EGFR in cancer cells, our finding of MDM2 as a negative regulator of DYRK1A may also bear implications in the management of the conditions associated with DYRK1A overexpression." (PMID 30910997, 2019). "Moreover, the nanoparticle based on co-delivery of EGFR drugs and integrin αvβ3 inhibitors also reveals great potential for use in the other chemotherapeutic agents, which provide a favorable platform for combined drugs delivery in cancer therapy." (PMID 31316001, 2019). "The epidermal growth factor receptor variant III (EGFRvIII), the most common mutation type of the epidermal growth factor receptor (EGFR), is highly overexpressed in malignant tumors (about 25% to 64% in glioblastoma), which may contribute to the aggressive and refractory course of GBM." (PMID 31579072, 2019).
cancer (continued). "Indeed, in many cancer cells, nuclear EGFR accumulates significantly more than in normal cells." (PMID 31426451, 2019). "Consequently, targeting EGFR or AKT could offer important approaches for cancer prevention and therapy." (PMID 31696057, 2019). "Recent advancements in the field of EGFR-targeted therapies have shown that various types of inhibitors can be administered to cure brain cancers; for instance, tyrosine kinase has been suggested to provide benefit for some patients whose cancers have particular genetic aberrations." (PMID 31013819, 2019). "Moreover, drug sensitivity, genetic, and histologic profiling of the SCLC-transformed EGFR mutants further suggests that chronic EGFR inhibition can lead to the development of cancers that adopt a classical SCLC genotype and phenotype than other TKI-resistant cell states." (PMID 31815659, 2019). "Anti-EGFR therapy in the context of cancer treatment may have cardiotoxic side effects, maybe due to EC dysfunction, because EGFR, which is normally involved in EGF/neuregulin signaling, can also form a holoreceptor with NRP1 and elicits a repellent SEMA3D signal in venous ECs." (PMID 30717262, 2019). "Several studies have showed that EGFR signaling regulates autophagy, a process involving sequestration and degradation of intracellular organelles and proteins in lysosomes, which function in cellular homeostasis and protection against a variety of disease including cancer." (PMID 31196210, 2019). "Therefore, this study showed how EGFR that is transactivated by a signal within the cytoplasm may activate the ErbB3-mediated signaling pathway in cancer cells with acquired resistance to cetuximab treatment." (PMID 31615015, 2019). "The inhibitory effect of psorachromene on the Erb-1 pathway indicates that it has considerable potential in the treatment of cancers that overexpress EGFR (including cancers of the breast and liver); it may also synergize with other anticancer drugs to enhance their therapeutic efficacy." (PMID 31750253, 2019). "Interestingly, transactivation of EGFR by GPCR has been reported in various cancers." (PMID 30845964, 2019). "Moreover, such EGFR levels were high in cisplatin refusal malignancies versus cancers sensitive to cisplatin; mainly because cisplatin is prone to activating tyrosine phosphorylation in the EGFR, which is responsible for fixing DNA damage upon treatment with cisplatin." (PMID 32148661, 2019). "Kang, D. has speculated that salidroside exerts anti-cancer effect by combing with EGFR site." (PMID 31214503, 2019). "Therefore, development of molecular inhibitors that can concurrently target EGFR’s kinase activity, impede dimerization of EGFR, and target EGFR for degradation may be of value to treat EGFR-positive cancers." (PMID 31121829, 2019). "Therefore, anti-EGFR compounds that reduce receptor protein levels might be an alternative strategy to interrupt aberrant signaling in cancer cells." (PMID 31374910, 2019). "Thus, EGFR has attracted great attentions as it is an ideal target for the cancer therapy." (PMID 31998131, 2019). "In addition to the EGFR pathway, PD-1 and PD-L1 constitute a potential target in cancer therapy." (PMID 31157216, 2019). "To this aim, we first tested the effects on cancer cell viability of the anti-EGFR CL4 aptamer in combination with a human anti-PD-L1 mAb named 10_12 to then verify whether a bispecific construct made up of these two moieties could be considered beneficial for anti-cancer treatment." (PMID 31470510, 2019). "Thus, EGFR is a candidate target for molecular-targeted therapy for these types of cancers." (PMID 31614999, 2019). "Interestingly, the podoplanin-mediated resistance of cancer cells to EGFR tyrosine kinase inhibitors depended on its cytoplasmic domain and required direct contact between CAFs and cancer cells, but the molecular mechanism for this effect remains to be elucidated." (PMID 30736372, 2019).
cancer (continued). "Moreover, some studies have revealed that IL-6 and HGF could help cancer cells to acquire the ability of anoikis resistance, suggesting bypass signaling in the EGFR pathway may play a significant role in anoikis resistance." (PMID 31198634, 2019). "Moreover, due to the loss of Tks4 having similar effects on cancer cells as EGF treatment (EMT induction, reduced E-cadherin expression), it is possible that Tks4 plays a putative negative regulatory role in the EGFR pathway by delaying signal transduction or changing its kinetics." (PMID 31671862, 2019). "Besides, maintenance or stabilization of EGFR expression is an important mechanism through which cancer cells could evade anoikis." (PMID 30237423, 2018). "Therefore, EGFR has been regarded as a central target for cancer therapy." (PMID 29552307, 2018). "Interestingly, cell culture model systems and clinical sample studies show that ALDH1A1-positive cancer stem cells promote significant resistance to both EGFR-TKI (gefitinib) and other anticancer chemotherapy drugs (cisplatin, etoposide, and fluorouracil) than ALDH1A1-negative cells in lung cancer." (PMID 29681949, 2018). "The possible pro-oncogenic functions of Smurf2 in genetically-compromised tumor cells could be related to the reported ability of Smurf2 to interfere with the RAS, Wnt/β-catenin, and EGFR-mediated signaling pathways, three central modules in cancer progression and chemoresistance." (PMID 30116722, 2018). "Moreover, autophagy induced by anti-EGFR mAbs acts as a protective response in cancer cells." (PMID 30427914, 2018). "This approach could be particularly effective in reducing the aggressiveness of cancer cells characterized by the pathological activation of EGFR signaling pathways or high levels of this receptor, as the case of basal-like cells which represent the majority of TNBCs." (PMID 29674627, 2018). "For example, first- and second-generation EGFR tyrosine kinase inhibitors (EGFR-TKIs) erlotinib (Tarceva), gefitinib (Iressa), afatinib, and dacomitinib have been used in clinic for the treatment of different cancers, offering new therapeutic approaches and an effective long-term cancer therapy." (PMID 29904349, 2018). "In addition, Cetuximab, an EGFR inhibitor used for the treatment of cancer, could also inhibited the uPA’s activity of stimulating migration, which further verified the LMW-uPA-induced cell migration was through EGFR-ERK1/2 pathway." (PMID 30241478, 2018). "However, how NEDD4 mediates the EGFR-dependent cancer cell migration remains elusive." (PMID 29455656, 2018). "Meanwhile, whether Fas has a role in EGF-dependent EGFR activation in cancer remained unknown." (PMID 30127519, 2018). "We identified protein kinases in need of further curation as well as kinase functional domains where aberrant PTM may contribute to disease; furthermore, we proposed testable hypotheses about cancer variants altering key PTM sites and experimentally tested the hypotheses in EGFR and PKCβ." (PMID 29695735, 2018). "Moreover, joined effects of c-Met and EGFR on inhibiting cancer cell metastatic ability could be carried out by repressing miR-200 family and methylcytosine dioxygenases (also called ten-eleven translocases, TET)." (PMID 29855336, 2018). "It turned out that cancers from virtually all responders carried by then unknown intragenic mutation in EGFR gene, while non-responders were characterized by the wild-type EGFR sequence." (PMID 30211169, 2018). "Thus, GPR119 agonist-mediated lactate production may lead to autophagy inhibition and potentiated cancer cell apoptosis with EGFR-TKI." (PMID 30497501, 2018). "Some previous studies have identified the biochemical links between Nox4 and cancer through several mechanisms, including angiogenesis, inflammatory cytokines, apoptosis resistance, histone modification, transforming growth factor-β and epidermal growth factor receptor pathway and so forth." (PMID 30513726, 2018).
cancer (continued). "Considering the immense contribution of EGFR to cancer, the establishment of α2-6 sialylation as a novel EGFR regulatory mechanism could advance a fundamental understanding of the relationship between growth factor signaling and cancer cell behavior." (PMID 29402301, 2018). "Cetuximab has been reported to show high binding affinity for EGFR highly expressed in cancer cells, provided that EGFR has no ectodomain mutations preventing cetuximab binding, although EGFR ectodomain mutations are rarely observed in patients' gastrointestinal cancers." (PMID 29989003, 2018). "Hence, we disclose a regulatory signaling cross talk between EGFR and EpCAM in cancer cells that impacts proliferation and EMT and may thus have substantial repercussions on disease progression and outcome." (PMID 30261040, 2018). "Moreover, co-expression of NGcGM3 and EGFR is a relatively frequent phenomena in cancer patients and what it is more relevant the over-expression of both EGFR and NGcGM3 variant correlates with a worst prognostic in NSCLC patients than the overexpression of either of these molecules separately." (PMID 29844873, 2018). "And in human cancer cells, kinase-independent EGFR could promote autophagic cell survival." (PMID 30237423, 2018). "For our glyco-engineered anti-PD-L1 antibody we found an enhanced NK cell-mediated ADCC against PD-L1+ cancer cells compared to the normal glycosylated variant, which is in line with the well-established superior ADCC capacity of several glyco-engineered antibodies (e.g., anti-CD20, anti-EGFR)." (PMID 30061887, 2018). "Previous drugs developed to impede tyrosine kinase activity for cancer treatment have had limited success, as one of the major challenges is the presence or development of resistance to treatment with long-term use, such as acquired resistance to epidermal growth factor receptor (EGFR) inhibitors." (PMID 29946469, 2018). "Indeed, PHLDA2 overexpression suppresses anchorage-independent cell growth and decreased PHLDA2 expression results in increased cell proliferation and reduced sensitivity to targeted agents of EGFR/ErbB2-driven cancers demonstrating functional relevance for this interaction." (PMID 29861842, 2018). "More recently, the Lin group used a functional genomics approach to identify a transmembrane protein of unknown function, TMEM43 (also referred as LUMA) as a new CARMA3-binding partner that serves as a critical mediator of EGFR-induced NF-κB activation in cancer cells." (PMID 30158935, 2018). "However, if it does, nano-conjugation of EGFR antibodies to pharmacological agents may provide a targeted approach to treating these cancers." (PMID 30544639, 2018). "This study identifies anti-mitophagy as a kinase-independent function of EGFR, reveals a novel function of mTORC2/Akt axis in promoting mitophagy in cancer cells, and offers a novel approach for pharmacological downregulation of EGFR protein as a potential treatment for EGFR-positive cancers." (PMID 29358623, 2018). "Previous studies have shown that the expression of the ABCG2 protein in various cancer cell lines is mediated by the activation of c-jun N-terminal kinase, mitogen-activated protein kinases, phosphate and tensin homolog, epidermal growth factor receptor and human epidermal growth factor (EGFR)." (PMID 30181510, 2018). "Therefore, targeting the EGFR pathway constitutes a potential treatment modality for human cancers." (PMID 30518879, 2018). "Moreover, we observed a positive association of SOX2 with EGFR expression in stage IV metastatic endometrial carcinoma, but not in early stage cancer." (PMID 30510261, 2018). "Thus, this chip is useful for the capture of mesenchymal-like cells, even though a range of cancer type which anti-EGFR antibody can capture may be narrower than that anti-EpCAM antibody captures." (PMID 30104638, 2018). "Importantly, EGFR-mediated YAP/TAZ activity can drive cancer development and progression." (PMID 29642615, 2018).